SPEGNB (SPEG neighbor)
Gene: Protein-coding gene on chromosome 2 (219,496,131 to 219,498,287, forward strand). Ensembl gene ENSG00000286095.
Gene Ontology:
Molecular function: protein kinase activity
Genetic constraint (gnomAD): Loss-of-function variants: 12 observed, 14.99 expected, observed/expected ratio (o/e) 0.8, 90% interval 0.51 to 1.3. The upper end of that interval is the gene's LOEUF score, 1.3, which puts it in group 5 of 6, group 1 being the genes least tolerant of losing a copy. Missense variants: 231 observed, 243.15 expected, observed/expected ratio (o/e) 0.95, 90% interval 0.85 to 1.06. Synonymous variants: 92 observed, 94.64 expected, observed/expected ratio (o/e) 0.97, 90% interval 0.82 to 1.16.
Homologues: Orthologues: chimpanzee SPEGNB (99% identical), macaque SPEGNB (97% identical), dog SPEGNB (96% identical), pig SPEGNB (92% identical), Caenorhabditis elegans ttn-1 (18% identical). Paralogues in human: PALLD (28% identical), MYPN (27% identical), HMCN1 (26% identical), OBSCN (24% identical), IGFN1 (24% identical), SPEG (24% identical), CCDC141 (19% identical), ALPK3 (15% identical), MYOT (9% identical).
Diseases named in the same sentence as SPEGNB in open-access papers:
SPEGNB is named in the same sentence as 2 diseases in open-access papers, as found by Europe PMC text mining. Sharing a sentence is not in itself a finding about the gene and the disease. The quoted sentences say what the papers report.
COVID-19 (1 paper, 2022). A disease caused by infection with severe acute respiratory syndrome coronavirus 2. "The potential involvement of SPEGNB in both hypertension and severe COVID-19 as well as it is relationship with SPEG warrants for further study." (PMID 36685827, 2022).
SPEGNB also shares sentences with these, for which no sentence is quoted: Hypertension (1 paper).